MIR6881 (microRNA 6881)
Synonyms: hsa-mir-6881
Gene: MicroRNA gene on chromosome 15 (74,411,357 to 74,411,432, reverse strand). Ensembl gene ENSG00000277391.
Homologues: Orthologues: chimpanzee MIR6881 (100% identical).